BDNF (brain derived neurotrophic factor)
Diseases named in the same sentence as BDNF in open-access papers (continued):
Sharing a sentence is not in itself a finding about the gene and the disease.
bipolar disorder (continued). "In fact, some authors associate progression in bipolar disorder-related cognitive decline with a greater reduction in BDNF signaling." (PMID 25202283, 2014). "An increase in CpG methylation at promoter regions on the BDNF gene have been found to be correlated with decreased neuronal synthesis of BDNF and with an increased risk of bipolar disorder." (PMID 23240009, 2012). "A candidate gene encoding Brain-Derived Neurotrophic Factor (BDNF) has been implicated in bipolar disorder and other psychiatric conditions." (PMID 22859933, 2012). "The first one is BDNF-LCPR (BDNF-linked complex polymorphic region), a 5′-UTR located microsatellite polymorphism, that is associated with an elevated risk of bipolar disorder and a lower transcription level of BDNF." (PMID 22087305, 2011). "The results of a study by Cao and colleagues pointed in this direction, since they discovered that bipolar disorder patients carrying the BDNF val66met met allele not only displayed deficits in memory performance, but also have a reduced volume of the hippocampus." (PMID 39194496, 2024). "In addition, regulating BDNF levels can provide a protective effect on bipolar disorders since BDNF elevation is associated with bipolar disorders." (PMID 39194500, 2024). "Furthermore, within patients with bipolar disorder we found a significant association between receiving anti-epileptic medication and higher BDNF levels." (PMID 33588978, 2021). "However G allele (major allele) has been reported to be associated with bipolar disorder and substance use with increased BDNF activity." (PMID 32171272, 2020). "Since both ketamine and amantadine block NMDA receptors, it can be speculated that it is the blocking of NMDA receptor function, in addition to increasing BDNF concentration, that is associated with the rapid effects of amantadine in bipolar depression." (PMID 33096753, 2020). "Evidence also suggests that BDNF overactivity in the brain may be implicated in the pathogenesis of bipolar disorder, substance abuse, and autism." (PMID 29867348, 2018). "Patients with bipolar disorder have significantly decreased BDNF in blood serum levels compared to healthy controls, and conversely lithium treatment is associated with increased serum BDNF protein in these patients." (PMID 30210290, 2018). "However, the higher activity BDNF Val allele is associated with bipolar disorder and substance use disorder." (PMID 29867348, 2018). "Moreover, both manic and depressive states in patients with bipolar disorder have been associated with significantly decreased BDNF blood serum levels compared to patients in euthymic states and healthy controls." (PMID 28621662, 2017). "BDNF and aberrant signaling through its high affinity receptor tropomyosin receptor kinase B (TrkB) have been proposed to underlie both the pathophysiology and treatment of bipolar disorder." (PMID 28621662, 2017). "Studies with larger samples and longitudinal studies evaluating normal and disrupted brain development, which include a control group and patients in different mood episodes, may be able to clarify the role of BDNF in brain changes caused by bipolar disorder." (PMID 26075097, 2015). "Furthermore, the association between BDNF levels and cognitive performance suggests that interventions designed to enhance neuroplasticity could improve cognitive outcomes in bipolar disorder." (PMID 41367212, 2025). "The observed similar behavioral phenotype after expression of mature and mutant forms of BDNF, together with the detected genes associated with bipolar disorder, supported that Bdnf could play a substantial role in the pathogenesis of this neurobehavioral disorder." (PMID 39619203, 2024). "Recent studies indicate involvement of miR-206-3p—a known regulator of BDNF signaling—in rat hippocampal response to the rapidly acting antidepressant ketamine, medial prefrontal cortex-mediated alcohol consumption in rats and susceptibility to bipolar disorder in human subjects." (PMID 28066174, 2016).
bipolar disorder (continued). "Furthermore, the BDNF polymorphism has been linked with disease severity, early adolescent onset, a propensity toward rapid cycling, and greater cognitive and executive function deficits in bipolar disorder." (PMID 25202283, 2014). "An association between a BDNF polymorphism and different neuropathological conditions such as Alzheimer's disease, obsessive-compulsive disorder, eating disorder and bipolar disorder has also been documented, as well as an association with executive functions in TBI subjects." (PMID 22087305, 2011). "Meta-analyses of clinical trials in patients with bipolar disorders showed that peripheral BDNF levels correlate with disease activity." (PMID 40076857, 2025). "In this study, we investigated the clinical and biological differences among cognitive subgroups in patients with bipolar disorder, focusing on the relationship between serum levels of BDNF and CRP." (PMID 41367212, 2025). "Reduced circulating BDNF levels have been reported in individuals with bipolar disorder during both manic and depressive episodes, showing a negative correlation with symptom severity, and have also been observed in patients with insomnia." (PMID 40699798, 2025). "Several studies show that plasma/serum BDNF is decreased in unipolar and bipolar depression and that after successful treatment, BDNF retrieves normal levels." (PMID 38500272, 2024). "Contrasting those reports, increased plasma BDNF levels were shown in patients with prolonged bipolar depression (over 20 years)." (PMID 38500272, 2024). "Studies have shown that BDNF dysregulation plays a crucial role in bipolar disorder and schizophrenia." (PMID 39194500, 2024). "BDNF is known to increase synaptic plasticity, and it is implicated, together with the NMDA receptor, in unipolar and bipolar depression." (PMID 38500272, 2024). "Few controlled trials have assessed the benefits of Mindfulness Based Cognitive Therapy (MBCT) on cognitive functions and brain-derived neurotrophic factor (BDNF) in bipolar disorder (BD)." (PMID 38250270, 2023). "A decrease in brain‐derived neurotrophic factor (BDNF) serum levels has been reported during the mania episode of patients with bipolar disorder, along with a decrease in executive function and verbal memory." (PMID 37933420, 2023). "In another study with euthymic adolescents with bipolar disorder, a lower BDNF level was detected in their blood after taking lithium." (PMID 36790601, 2023). "Regarding bipolar depression, a large meta-analytical study showed that compared to healthy controls, peripheral BDNF level is reduced in manic and depressive episodes, while it is not significantly altered in euthymia." (PMID 35448545, 2022). "There have been many intergenerational animal studies, as well as a few human studies looking at maternal exposure as a modifier of offspring BDNF methylation, for example, studies of trauma and fear, bi‐polar disorder, and depressive symptoms." (PMID 35119793, 2022). "In the case of bipolar disorder, BDNF concentration levels are reduced both in manic and depressive states, while, in euthymia, they do not differ as compared with controls." (PMID 34640441, 2021). "The results contrast with prior findings of decreased BDNF levels in patients with advanced or progressed bipolar disorder and add to a more complex understanding of the possible influence of neurotrophins on the course of bipolar disorder." (PMID 33588978, 2021). "The aim of our present study was to investigate plasma BDNF levels in patients newly diagnosed with bipolar disorder, and their unaffected first-degree relatives, in comparison with healthy controls." (PMID 33588978, 2021). "The study investigated plasma BDNF levels in patients (n = 371) with newly diagnosed bipolar disorder, their unaffected first-degree relatives (n = 98) and healthy controls (n = 200) using enzyme-linked immunosorbent assay." (PMID 33588978, 2021).
bipolar disorder (continued). "In conclusion, we found increased BDNF levels in newly diagnosed patients with bipolar disorder and their unaffected first-degree relatives compared with healthy controls." (PMID 33588978, 2021). "When all participants were split according to gender, the significant difference in BDNF levels between patients with bipolar disorder and healthy controls was only statistically significant within women (P = 0.012)." (PMID 33588978, 2021). "In contrast with most prior studies investigating BDNF in patients with more progressed bipolar disorder, we found newly diagnosed patients to have elevated BDNF levels as compared with healthy controls." (PMID 33588978, 2021). "Studies have shown that the concentration of BDNF in the serum of patients with bipolar disorder is significantly lower than that of healthy people." (PMID 35194435, 2021). "The BIO study is the first study to investigate BDNF in patients who are newly diagnosed with bipolar disorder or with first-episode bipolar disorder and their unaffected first-degree relatives in comparison with healthy controls." (PMID 33588978, 2021). "The most frequently studied peripheral biomarkers in bipolar disorder, namely, inflammatory markers, oxidative stress markers, and BDNF, are also relevant to CVD." (PMID 32356562, 2020). "A systematic review and meta‐regression analysis (n = 548 bipolar disorder, n = 565 controls) reported reduced BDNF with large effect sizes (ES) for mania (ES –0.81) and depression (ES –0.97) vs controls." (PMID 32356562, 2020). "Five of 50 patients with bipolar disorders exhibited three copies of the genomic region within exon IV of the BDNF gene." (PMID 31769621, 2020). "As with adults, there is evidence that inflammation is elevated and BDNF is reduced in youth with bipolar disorder." (PMID 32356562, 2020). "The study also revealed that miR-7 regulates the expression of brain-derived neurotrophic factor (BDNF), and its concentration influences the pathophysiology of bipolar disorders through an autoregulatory mechanism." (PMID 31980721, 2020). "Antioxidant enzymes activities, brain-derived neurotropic factor (BDNF) levels, and mitochondrial DNA copy number (mtDNAcn) in bipolar disorder (BD) patients and healthy controls." (PMID 33061913, 2020). "An earlier report demonstrated that circulating BDNF is diagnostic biomarker for major depressive disorders MDD and bipolar disorder (BD)." (PMID 31199848, 2019). "Among these were BDNF, VGF, WFS1, DUSP6, CRHBP, MAOA, and RELN, which have previously been implicated in bipolar disorder." (PMID 31114610, 2019). "In a study sampling patients with MDD as well as bipolar disorder, patients with MDD had higher BDNF exon I promoter methylation levels than patients with bipolar disorder and healthy controls." (PMID 31027379, 2019). "The majority of studies on neurotrophins in bipolar disorder have focused on brain derived neurotrophic factor (BDNF)." (PMID 30113291, 2018). "BDNF is significantly decreased in both mania and bipolar depression, whereas TNF-α is raised in mania and bipolar depression, and neither are significantly different from levels in controls in euthymia." (PMID 30113291, 2018). "Previous meta-analyses have investigated specific biomarkers in bipolar disorder, including hsCRP, cytokines, BDNF and oxidative stress markers." (PMID 30113291, 2018). "Meta-analyses with three or more studies were performed for BDNF, IL-4, TNF-α and IFN-γ in patients with mania and BDNF for bipolar depression." (PMID 30113291, 2018). "Previous work has shown that patients with bipolar disorder have decreased peripheral BDNF mRNA in blood lymphocytes and monocytes in comparison to healthy controls." (PMID 28621662, 2017). "Post-mortem analysis of hippocampal tissue has also revealed reduced BDNF protein levels in patients with bipolar disorder." (PMID 28621662, 2017).
bipolar disorder (continued). "For instance, there appears to be oxidative stress, decreased BDNF levels, and telomere shortening in the later stages of bipolar disorder." (PMID 29156546, 2017). "We explored the effect of the Brain-derived neurotrophic factor (BDNF) Val66Met polymorphism (rs6265) on correlation between changes in plasma BDNF levels with cognitive function and quality of life (QoL) after 12 weeks of treatment in bipolar disorder (BD)." (PMID 27905499, 2016). "One of the best candidates for explaining the relationship of exercise with neurogenesis—to ultimately improve outcomes in bipolar disorder—is BDNF." (PMID 25788889, 2015). "We conducted a systematic review and meta-analysis of all studies on serum and plasma BDNF levels in bipolar disorder." (PMID 26621529, 2015). "In subjects with bipolar disorder, lower serum BDNF levels were found when the subjects were in both the manic or depressive state compared with normal controls." (PMID 26866045, 2015). "Current literature on BDNF and mental disorders is particularly focused on depressive and bipolar disorders." (PMID 25734326, 2015). "Although both plasma and serum BDNF levels are decreased in acute major and bipolar depression, they seem to restore differently following antidepressant treatment." (PMID 26529101, 2015). "BDNF has been found to be decreased in lymphocytes and platelets of patients with pediatric bipolar disorder compared to controls." (PMID 26866045, 2015). "Findings of studies investigating peripheral GDNF levels in bipolar disorder are less consistent than those in BDNF research." (PMID 25202283, 2014). "Patients with unipolar or bipolar depression exhibit decreased brain-derived neurotrophic factor levels." (PMID 23408933, 2013). "Our study examined the effect of the BDNF Val66Met genotype on regional brain volumes in a cohort of 230 subjects, of which 166 were diagnosed with bipolar disorder and the rest were healthy controls." (PMID 22859933, 2012). "For example, chronic, but not acute, lithium treatment increases BDNF expression in the rat hippocampus and temporal cortex, and BDNF expression has been observed following 28days of lithium treatment in persons with bipolar disorder." (PMID 21935433, 2011). "A low concentration of BDNF is also regarded as a marker of late-stage bipolar affective disorder." (PMID 40283904, 2025). "In this review, we aimed to collect all available data on BDNF and bipolar disorder (BD) and assess if BDNF could be considered a biomarker for BD." (PMID 37626577, 2023). "However, a recent review and meta-analysis of 35 studies highlights the limitations of the available evidence, suggesting moderate conclusions regarding the role of peripheral BDNF as a biomarker in bipolar disorder and calls for further research in this area." (PMID 38250270, 2023). "Likewise, some other reports have shown an increased level of BDNF after completion of ECT therapy in patients with MDD or in patients with bipolar disorder (BDNF levels were measured in the depressive state)." (PMID 37685795, 2023). "Moreover, recent reports demonstrated that the BDNF gene (Val66Met) was related to changes in gyrification in bipolar disorder." (PMID 36684011, 2022). "BDNF is one of the most widely studied neurotrophins in neuropsychiatric disorders, and reduced peripheral blood concentrations have been found in schizophrenia, bipolar disorder, and major depression." (PMID 34989854, 2022). "BDNF levels were found to be 22.0% (95% CI 1.107–1.343) higher in patients with bipolar disorder compared with healthy controls (P < 0.001) and 15.6% higher in unaffected first-degree relatives compared with healthy controls (95% CI 1.007–1.327, P = 0.04), when adjusting for age and gender." (PMID 33588978, 2021). "However, there was a statistically significant positive association between longer illness duration (years) and higher BDNF levels in participants with bipolar disorder (R = 1.000, P = 0.05)." (PMID 33588978, 2021).
bipolar disorder (continued). "Furthermore, when only including patients who did not receive any psychotropic medication (n = 64) in the mixed linear models, the difference in BDNF levels between patients with bipolar disorder and healthy controls lost significance (P = 0.4)." (PMID 33588978, 2021). "The findings did not support our first hypothesis, that newly diagnosed patients with bipolar disorder would have lower BDNF levels compared with healthy controls." (PMID 33588978, 2021). "Furthermore, a meta-analysis of 52 studies indicates that peripheral BDNF level, better documented in plasma than in serum, is a potential biomarker of disease activity in bipolar disorder." (PMID 34526917, 2021). "Teixeira et al4 reviewed the current state of peripheral (blood‐derived), genetic, neuroimaging, and neurophysiological candidates for biomarkers of bipolar disorders and found several promising candidates, including peripheral inflammation markers and Brain‐Derived Neurotrophic Factor (BDNF)." (PMID 31449716, 2020). "Both higher BDNF methylation and lower BDNF protein levels are associated with worse neurobehavioral outcomes in children with preterm birth, attention-deficit/hyperactivity disorder (ADHD), bipolar disorder, anorexia, and autism spectrum disorder." (PMID 32595586, 2020). "They found that the BDNF Val66Met polymorphism is significantly associated with bipolar disorder in Europeans, but not in Asians." (PMID 29867348, 2018). "Patients with bipolar disorder often have low levels of a protein called brain-derived neurotrophic factor, or BDNF for short, which plays an essential role in keeping the brain healthy, and may also regulate the connections between neurons." (PMID 28621662, 2017). "Furthermore, a recent meta-analysis reports that the peripheral blood levels of BDNF in patients with bipolar disorder with manic and depressive episodes are decreased, but those with euthymia are not altered compared to healthy controls." (PMID 27777607, 2016). "BDNF is being considered a potential candidate as a biomarker for bipolar disorder." (PMID 26075103, 2015). "Among hypothesized pathways of exercise and bipolar disorder is epigenetics as exercise may elevate BDNF via these mechanisms." (PMID 25788889, 2015). "Nonetheless, it is intriguing that elevation of inflammatory cytokines in the CNS has been associated with suppressed synthesis of neurotrophic factors (especially BDNF) and compromised monoaminergic transmission, both of which have been reported in bipolar disorder." (PMID 25202283, 2014). "In the later stages of bipolar disorder, an imbalance between inflammatory cytokines (especially TNF-alpha), mediators of oxidative stress, and BDNF persists even between episodes and is associated with metabolic disruption, progression of structural brain changes, and neurocognitive decline." (PMID 25202283, 2014). "However, there are several areas regarding the role of BDNF in bipolar disorder that need further clarification." (PMID 25202283, 2014). "Indeed, serum BDNF levels were lower in bipolar disorder patients during an acute depressive episode than in patients diagnosed for MD." (PMID 22654714, 2011). "Although preliminary, a recent study suggests that decreased BDNF gene expression may play a role in the pathophysiology of bipolar disorder in children." (PMID 19193231, 2009). "Furthermore, treatment with mood stabilizers normalized BDNF mRNA level at 8 weeks and change in symptoms of bipolar disorder was correlated with change in BDNF mRNA levels." (PMID 19193231, 2009). "Manic depression has a successful therapy in lithium, which might have been shown to increase BDNF." (PMID 37287291, 2024). "Moreover, given the involvement of BDNF signaling in coordinating gamma activity, we expect that future studies examining oscillatory activity in this rodent model of bipolar disorder may reveal reductions in gamma activity induced by cannabinoid exposure." (PMID 33613338, 2021).